CCNB1 (cyclin B1)
Diseases named in the same sentence as CCNB1 in open-access papers (continued):
Sharing a sentence is not in itself a finding about the gene and the disease.
breast carcinoma (continued). "The CCNB1 protein level has been shown to differ among breast cancer subgroups and different histological grades." (PMID 36360219, 2022). "CCNB1 is a biomarker for the prognosis of ER+ breast cancer and monitoring of hormone therapy efficacy." (PMID 38091511, 2022). "Our results showed that the expression of CCNB1 was elevated in many cancers compared to normal cases, such as esophageal cancer, gastric cancer, colorectal cancer, liver cancer, and breast cancer." (PMID 35983531, 2022). "After these analyses, we believe that CCNB1 is superior as a breast cancer prognostic biomarker over other genes." (PMID 36040381, 2022). "CCNB1 and CDK1 were co-expressed in ACC, and this action was also acknowledged in breast cancer susceptibility, progression, and survival of Chinese women." (PMID 35983531, 2022). "The EVO-PLGA NPs formulation was able to down-regulate the β-actin expression and upregulate the cyclin B1 expression that proving its effectiveness for the treatment of breast cancer therapy." (PMID 34960948, 2021). "Some studies have found that CCNB1 expression is increased in different types of cancer, such as breast cancer and gastric cancer." (PMID 34257537, 2021). "Both univariate and multivariate analyses significantly identified an increased breast cancer death rate correlated with cyclin B1 overexpression, suggesting that it serves as a remarkable prognostic factor." (PMID 33920506, 2021). "Recently, increasing evidence demonstrated that CCNB1 was over-expressed in considerable cancers with poor prognosis, including hepatocellular carcinoma, breast cancer, and pancreatic cancer." (PMID 34126961, 2021). "Further, siRNA-based silencing of CCNB1 partially recapitulated CHK1i-resistant phenotype in parental cells, similar to the reports in prostate cancer or breast cancer models." (PMID 32647134, 2020). "For example, CCNB1 has strong power to predict the survival of breast cancer patients with the phenotype of ER positive." (PMID 32461838, 2020). "Amongst the other highly significant upregulated CR genes by p-value and log2FC, SKA2, MKI67, HJURP, BIRC5, and CCNB1 are upregulated in breast cancer tissues and all five except for SKA2 have been identified as prognostic markers for breast cancer." (PMID 32457901, 2020). "Present study revealed significant down-regulation of cell cycle and DNA damage response genes, including E2F1, E2F2, RAD51, and CCNB1 in breast cancer cells treated with palbociclib." (PMID 31548560, 2019). "The up-regulation of cyclin B1/Cdc2 plays a pivotal role in treated breast cancer cells in human in stagnation of Mitotic Prometaphase." (PMID 31888692, 2019). "CCNB1 has also been demonstrated to have significant predictive power in overall survival of ER+ breast cancer patients and HBV-related HCC recurrence." (PMID 30651720, 2019). "Derived from exon 4 and exon 5 of the CCNB1 gene, the circRNA circ-Ccnb1 was downregulated in breast cancer and mainly localized in the nucleus in breast cancer cells." (PMID 30626395, 2019).
breast carcinoma (continued). "At the same time, there is evidence that inhibition of CCNB1 expression makes breast cancer cells more sensitive to the chemotherapy drug paclitaxel." (PMID 31007608, 2019). "Recent studies have shown that CCNB1 is highly expressed in several different human cancers including breast cancer, cervical cancer, lung cancer and melanoma." (PMID 30651720, 2019). "Based on integrated bioinformatic analysis, the present study has identified 321 DEGs and six hub genes (CDK1, CCNA2, TOP2A, CCNB1, KIF11, and MELK) that are associated with breast cancer tumorigenesis and progression." (PMID 31428132, 2019). "CCNB1 also has significant predictive power in monitoring hormone therapy efficacy and the prognosis of patients with ER+ breast cancer." (PMID 31007608, 2019). "Genistein is known to inhibit tumor growth in numerousmalignancies including breast cancer cell lines via G2/M cell cyclearrest and cyclin B1 downregulation." (PMID 31359993, 2019). "It is reported that CCNB1 is a power prognostic factor for the survival of ER+ breast cancer patients, and it is also involved in therapy resistance." (PMID 29467930, 2018). "By microarray analysis and real-time PCR, we detected decreased circ-Ccnb1 expression levels in patients bearing breast carcinoma." (PMID 29795334, 2018). "At molecular levels, knockdown of UBAP2L increased p21 expression, but decreased the expression of CDK1 and Cyclin B1 in breast cancer cells." (PMID 29196913, 2018). "We further demonstrate that treatment of Brca1-mutant mammary tumors with vinblastine, which induces cyclin B1, significantly reduced tumor progression." (PMID 30327455, 2018). "We further characterized the interaction of BRCA1 and cyclin B1 and performed preclinical tests of vinblastine, a cyclin B1-inducing agent, in the treatment of BRCA1-associated mammary tumors using a Brca1-mutant allograft model." (PMID 30327455, 2018). "Treatment of Brca1-mutant mammary tumors with vinblastine, which alters cyclin B1 level, significantly reduced tumor progression with reduction of survival and induction of apoptosis." (PMID 30327455, 2018). "MYB has been reported to directly activate the expression of CCNE1 (in normal and transformed colonic epithelium and CCNB1 (in leukaemia and breast cancer cells;." (PMID 26812885, 2016). "According to our results, YB1 CTD markedly decreased cell cycle‐promoting factor cyclin B1 levels and increased cyclin‐dependent kinase inhibitor p21 levels in SK‐BR‐3 breast cancer cells, which inhibited SK‐BR‐3 cell proliferation." (PMID 27047740, 2016). "CENPE overexpression was correlated with cyclin B1 expression and is related to poor prognosis in breast cancers." (PMID 26933822, 2016). "Knockdown of endogenous YB1 resulted in reduced cyclin B1 protein level and decreased proliferation activity in SK‐BR‐3 breast cancer cells." (PMID 27047740, 2016). "ATF2 has been reported to modify Cyclin B1 and Cyclin D1 levels to promote cell-cycle progression in several types of neoplasms, including cervical and breast cancer." (PMID 27377902, 2016). "Further, it has also been shown that knock down of MUC16 in breast cancer cells resulted in a decrease of Cyclin B1 and activation of Aurora Kinase A levels." (PMID 27382435, 2016). "Accumulated evidences have showed that Cyclin B1 were overexpressed in breast cancer, esophageal squamous cell carcinoma, lung cancer, gastric cancer, hepatocellular cancer, and other cancer cells." (PMID 25962181, 2015).
breast carcinoma (continued). "A role for the CDK1/cyclin B1 complex in WA-dependent growth inhibition and G2/M cell cycle arrest in breast cancer cells has already been reported." (PMID 24498382, 2014). "Cyclin B1 expression was investigated in a subset of breast tissue specimens (n=84), with expression levels found to be up-regulated in breast cancer compared to normal and benign breast tissue." (PMID 23874748, 2013). "Transfection of a breast cancer cell line with a miR-379 mimic resulted in reduced Cyclin B1 protein expression and inhibition of proliferation, supporting a role for miR-379 in direct regulation of Cyclin B1." (PMID 23874748, 2013). "Allele and genotype frequencies of the selected tSNPs in CCNB1 and CDK1 and the association with risk of breast cancer." (PMID 24386390, 2013). "miR-379 has a putative binding site on Cyclin B1 which is a key initiator of mitosis and has previously shown a relationship with tumour stage and grade in breast cancer." (PMID 23874748, 2013). "Functional assays revealed reduced proliferation (p<0.05) and decreased Cyclin B1 protein levels following transfection of breast cancer cells with miR-379." (PMID 23874748, 2013). "Recent studies have demonstrated aberrant expression of cyclin B1 in several malignant cancers, including breast cancer, esophageal squamous cell carcinoma, non-small cell carcinoma, gastric cancer, and hepatocellular carcinoma." (PMID 22682366, 2012). "Using the GSA-Cell line application, we investigated CCNB1 mRNA expression levels across the breast cancer cell line panel." (PMID 21445301, 2011). "Most relevant to breast cancer is the suppression of pathway member cyclin B1 in miR-342 expressing MCF-7/HER2Δ16 cells." (PMID 21172025, 2010). "In conclusion, this study shows that cyclin B1 expression is an independent predictor of poor overall and metastasis-free survival in breast cancer." (PMID 19293801, 2009). "The studies of cyclin B1 expression in breast cancer strongly suggest a prognostic role but these studies have been rather small." (PMID 19293801, 2009). "Correlation of cyclin B1 expression with other histopathological variables and prognostic role in breast cancer are not fully understood." (PMID 19293801, 2009). "In this study we investigated cyclin B1 expression, its correlation with other histopathological features and survival in an extensive series of 1348 breast cancers (779 cancers in survival analysis)." (PMID 19293801, 2009). "A recent study with 109 breast cancers suggested that nuclear cyclin B1 expression was an independent prognostic factor." (PMID 19293801, 2009). "The independent prognostic value of cyclin B1 in this study was as strong as or even stronger than the risks reported for commonly used biological markers in breast cancer." (PMID 19293801, 2009). "Breast cancer cells in which the Notch pathway has been targeted, either by an inhibitor of γ-secretase or by Notch-1 RNAi, downregulate cyclin B1 and suffer G2/M arrest." (PMID 19513078, 2009). "This study is so far the most extensive study of cyclin B1 expression in breast cancer and shows that high cyclin B1 expression is a predictor of poor overall and metastasis-free survival." (PMID 19293801, 2009). "After combining cyclin B1 siRNA with taxol, we observed an increased apoptotic rate accompanied by an enhanced antiproliferative effect in breast cancer cells." (PMID 19113992, 2008). "Downregulation of cyclin B1 inhibits proliferation of tumor cells in vitro as well as in vivo and sensitizes breast cancer cells to taxol." (PMID 19113992, 2008). "For example, L1CAM, GATA4, CCNB1, CDKN1C, and FEN1 have been reported for their association with breast cancer: L1CAM was shown to inhibit the growth of breast carcinoma cells." (PMID 18237428, 2008). "CCNB1 was reported to be upregulated in MCF-IR20 breast cancer cells by microarray experiment and to significantly reduce the clonogenic survival of MCF-IR20 cells." (PMID 18237428, 2008).
breast carcinoma (continued). "Among the breast cancer cells we used, T47D cells demonstrated the greatest over-expression and cytoplasmic accumulation of cyclin B1." (PMID 17129372, 2006). "Recent studies have established a correlation between radioresistance of breast cancer cells and induction of both NF-κB and cyclin B1 and demonstrated that fractionated radiation induced cyclin B1 expression via an NF-κB-dependent mechanism." (PMID 16640785, 2006). "Evidence is accumulating that naturally occurring immunity is present in patients with breast cancer against tumor associated antigens such as HER-2/neu and cdr2, as well as the antigens investigated here, namely MUC-1, cyclin B1 and survivin." (PMID 17129372, 2006). "A recent report that the expression of cyclin-B1 in breast cancer cells was sustained in the G1 phase suggests that the cell cycle can progress in the presence of an abnormal mitotic cell cycle machinery." (PMID 15743504, 2005). "Additionally, CCNB2 has been linked to metastasis in nasopharyngeal cancer, breast cancer, and non-small-cell lung cancer; PLK1 in pancreatic cancer and melanoma; and CCNB1 in esophageal cancer." (PMID 40076867, 2025). "In breast cancer, RYBP overexpression has been associated with tumor suppression by inhibiting cell proliferation and metastasis via the regulation of proteins such as cyclin A, cyclin B1, and E-cadherin." (PMID 40867231, 2025). "Interestingly, we see that 2ME upregulates JNK1, an important up-stream activator of cyclin B1 and cdc2, and is responsible for 2ME-induced endoreduplication in human breast cancer cells." (PMID 38994940, 2024). "The results of the present study show that autophagy initiated by d-arabinose is accompanied by down-regulation of Cyclin B1 and up-regulation of p21 and p27, suggesting that d-arabinose may modulate autophagy via cell cycle regulators in breast cancer cells." (PMID 38755221, 2024). "CCNB1 expression is elevated in breast cancer tissue, and the expression of this biomarker demonstrates a significant correlation with patient survival time, tumor burden, methylation, infiltration of immune cells, as well as the absence of estrogen receptor expression." (PMID 38609711, 2024). "Moreover, elevated levels of CCNB1 and PLK-1 are known to be strongly associated with low overall survival in other solid tumors like breast cancer, demonstrating their potentiality as prognostic markers and as combinatorial drug targets." (PMID 39684470, 2024). "Furthermore, CCNB1 overexpression contributes to resistance to radiotherapy in head and neck squamous cell carcinoma, and nuclear cyclin B1-positive breast carcinomas are resistant to adjuvant therapy." (PMID 39795587, 2024). "Both CENPL and CCNB1 have been found to be upregulated in breast cancer tissues." (PMID 36982402, 2023). "Indeed, the knockdown of FBXW9 increased p21 mRNA expression while mRNA levels of CCNA2 and CCNB1 were decreased in breast cancer cells." (PMID 36982338, 2023). "Starting with the observation that A3B expression is heterogeneous in cultured breast cancer cells, we show that A3B expression associates strongly with Cyclin B1 and not Cyclin E2 on a single-cell level in cell lines and clinical breast cancer specimens." (PMID 37190094, 2023). "In addition, FOXM1 regulates downstream proteins, including survivin, RAD51, which contribute to homologous recombination DNA repair in breast cancer cells and, cyclin B1, a cell cycle regulatory protein." (PMID 37242455, 2023). "Moreover, knockdown of cyclin B1 inhibited breast cancer cell proliferation by sensitizing them to chemotherapeutics." (PMID 37242455, 2023). "This study also found that decreased cyclin B1 sensitized breast cancer cells to taxol." (PMID 37049472, 2023). "Interestingly, there have been reports confirming the carcinogenic effect of high expression of CCNB1 in various cancers, including renal cancer, breast cancer, pancreatic cancer, hepatocellular carcinoma, and cervical cancer." (PMID 37592341, 2023).
breast carcinoma (continued). "The present study convincingly revealed that d-limonene inhibits the growth of MCF7 breast cancer cells and arrest the cell cycle at the G2/M phase by inhibiting Cyclin B1/ CDK1 complex through their influential effect on structure and function leading to induction of apoptosis." (PMID 36307489, 2022). "The expression of key markers associated with proliferation (MKI67, PCNA, CCNB1, MYBL2, BUB1, CCND1), apoptosis (BCL2, CASP7, CASP8, CASP9, CASP3, BAX, APAF1), differentiation (CDH1, CD24, EPCAM, ESR1, NGFR, RUNX1), and breast cancer stemness (CD44, ITGA6, DNER, ALDH1A3, ABCG2, PROCR) was assessed." (PMID 35183258, 2022). "The role of CCNB1 in breast cancer progression is also reported." (PMID 35456460, 2022). "Material and Methods: We evaluated the transcriptional, survival data and expression levels in tissue data of CCNB1 in patients with breast cancer from the Gene Expression Omnibus (GEO), The Cancer Genome Atlas (TCGA), The Human Protein Atlas (THAP) and Genome Tissue Expression (GTEx) database." (PMID 36040381, 2022). "circ-CCNB1 has been reported to inhibit breast cancer cell proliferation and invasion." (PMID 35731831, 2022). "In addition, elevated Ccnb1 levels, as was seen in the aged gastric organoids of the current study, have been frequently seen in advanced gastric cancers and breast cancers." (PMID 36923312, 2022). "Besides, upregulated cyclin B1 in solid tumors are also related to poorer prognoses including but not limited to breast cancer, gastric cancer, and esophagus carcinoma." (PMID 34131395, 2021). "A study showed that CCNB1 could be used as a prognostic factor of breast cancer death, with good repeatability." (PMID 34797837, 2021). "Another study demonstrated that CCNB1 regulated cell cycle progression in breast cancer." (PMID 34354775, 2021). "Moreover, the cyclin B1 protein, which is necessary for G2/M passage, is also positively regulated by E2 in breast cancer cells." (PMID 34678933, 2021). "Plenty of evidence indicates that CCNB1/2 dysfunction is an early event in tumorigenesis, and its unregulated expression could be observed in many human tumours, including breast cancer, lung cancer and brain cancer." (PMID 33449451, 2021). "Additionally, we demonstrated that usenamine A decreased the expression of Cyclin B1 and Cyclin A in breast cancer cells, leading to cell cycle arrest at the G2/M phase." (PMID 34572561, 2021). "We have found that the combination of alteronol and ADM significantly suppressed the expression levels of the cell cycle-related proteins (CDC2 and Cyclin B1) and induced cell cycle arrest at the G2/M phase, leading to cell proliferation inhibition in breast cancer 4T1 cells." (PMID 31001113, 2019). "CCNB1 has been known to be associated with breast cancer, but so far there is little or no direct relation known between CCNB1 and TERT." (PMID 31856825, 2019). "In addition, CCNB1 can also serve as a prognostic biomarker for oestrogen receptor positive (ER+) breast cancer." (PMID 31585531, 2019). "In parallel, evidence has showed that inhibition of CCNB1 expression renders breast cancer cells more sensitive to chemotherapy drug taxol, and CCNB1 is a biomarker for the prognosis of ER + breast cancer and monitoring of hormone therapy efficacy (Ding, Li, Zou, Zou, & Wang, 2014)." (PMID 30556321, 2019). "CCNB1 is known to be an ERβ response gene in breast cancer cells." (PMID 31696058, 2019). "Quantitative analysis of transcript abundance among the three sub-populations of OR genes confirmed that the genes associated with breast cancer cell proliferation (MKI67, AURKA, BIRC5, CCNB1, MYBL2) were significantly abundant in sub-population I with OR2B6 upregulation." (PMID 31551495, 2019).